B9D2 (B9 domain containing 2)
Description:
Component of the tectonic-like complex, a complex localized at the transition zone of primary cilia and acting as a barrier that prevents diffusion of transmembrane proteins between the cilia and plasma membranes.
Synonyms: MKSR2; MGC4093; MKS10; MKSR-2; ICIS-1; JBTS34
Tractability: No criterion of Open Targets' tractability assessment is met for any kind of drug.
Gene: Protein-coding gene on chromosome 19 (41,354,417 to 41,364,165, reverse strand). Ensembl gene ENSG00000123810.
Subcellular location: Cytoplasm, cytoskeleton, cilium basal body; Cytoplasm, cytoskeleton, cilium axoneme; Nucleus
Subcellular location (Human Protein Atlas): Golgi apparatus; Nucleoli; Basal body; Centrosome; Vesicles
Pathways (Reactome):
Cell Cycle: Amplification of signal from unattached kinetochores via a MAD2 inhibitory signal; EML4 and NUDC in mitotic spindle formation; Mitotic Prometaphase; Resolution of Sister Chromatid Cohesion; Separation of Sister Chromatids
Organelle biogenesis and maintenance: Anchoring of the basal body to the plasma membrane
Signal Transduction: RHO GTPases Activate Formins
Gene Ontology:
Molecular function: protein binding; gamma-tubulin binding
Biological process: cilium assembly; protein localization to ciliary transition zone
Cellular component: centrosome; ciliary basal body; ciliary transition zone; cytosol; MKS complex; axoneme; cilium; membrane; nucleus
Genetic constraint (gnomAD): Loss-of-function variants: 21 observed, 19.89 expected, observed/expected ratio (o/e) 1.06, 90% interval 0.75 to 1.52. The upper end of that interval is the gene's LOEUF score, 1.52, which puts it in group 6 of 6, group 1 being the genes least tolerant of losing a copy. Missense variants: 219 observed, 253.21 expected, observed/expected ratio (o/e) 0.86, 90% interval 0.77 to 0.97. Synonymous variants: 91 observed, 102.04 expected, observed/expected ratio (o/e) 0.89, 90% interval 0.75 to 1.06.
Gene-disease validity (ClinGen):
ClinGen rates the evidence that B9D2 causes each of these diseases.
ciliopathy (autosomal recessive): Moderate. A genetic disorder of the cellular cilia or the cilia anchoring structures, the basal bodies, or of ciliary function.
Homologues: Orthologues: chimpanzee B9D2 (99% identical), macaque B9D2 (99% identical), mouse B9d2 (97% identical), pig B9D2 (95% identical), rat B9d2 (95% identical), guinea pig B9D2 (94% identical), rabbit B9D2 (94% identical), zebrafish b9d2 (75% identical), tropical clawed frog b9d2 (72% identical), Drosophila melanogaster B9d2 (45% identical), Caenorhabditis elegans mksr-2 (43% identical). Paralogues in human: MKS1 (36% identical), B9D1 (26% identical).
Diseases named in the same sentence as B9D2 in open-access papers:
B9D2 is named in the same sentence as 10 diseases in open-access papers, as found by Europe PMC text mining. Sharing a sentence is not in itself a finding about the gene and the disease. The quoted sentences say what the papers report.
ciliopathy (5 papers, 2019 to 2026). "b9d2 mutations reduce posttranslational modifications of the axonemal microtubules and cause ciliopathy phenotypes in zebrafish." (PMID 41165761, 2026). "Among the mutant lines in this study we found five genes which have been previously linked to human ciliopathies: B9d2, Cc2d2a, Rpgrip1l, Ift140 and Nek930." (PMID 31243271, 2019). "Previous research demonstrated that suppression of b9d2 using morpholino (MO) or KO of b9d2 induces ciliopathy-related developmental defects in zebrafish." (PMID 41165761, 2026). "In addition to this, 661W cells express several syndromic ciliopathy disease genes which are not expressed at all in hTERT-RPE1 cells, including B9d1, B9d2, Evc2, Pkd1, and Tmem138." (PMID 31024622, 2019).
Joubert syndrome (3 papers, 2021 to 2026). Joubert syndrome (JS) is characterized by congenital malformation of the brainstem and agenesis or hypoplasia of the cerebellar vermis leading to an abnormal respiratory pattern, nystagmus, hypotonia, ataxia, and delay in achieving motor milestones. "We found that Joubert syndrome–associated B9D2 variants primarily affected axonemal microtubule modifications without disrupting ciliogenesis, whereas the Meckel syndrome–associated B9D2 variant disrupted both ciliogenesis and axonemal microtubule modifications." (PMID 41165761, 2026). "In addition, we identified B9D2 variants in a cohort of patients with Joubert syndrome." (PMID 41165761, 2026). "Editor’s choice: Genome editing was carried out in C. elegans to model and characterise two pathogenic missense variants of mksr-2/B9D2, P74S and G155S, from a compound heterozygous patient with Joubert syndrome." (PMID 33234550, 2021).
Meckel syndrome (3 papers, 2021 to 2026). "B9D2 functions within the Meckel syndrome (MKS) module at the ciliary base transition zone (TZ) compartment and regulates the molecular composition and sensory/signalling functions of the cilium." (PMID 33234550, 2021). "Specifically, we have focused on the TZ gene B9D2, linked to both Joubert and Meckel syndromes (JBTS34 and MKS10; MIM#614175)." (PMID 33234550, 2021).
asthma (1 paper, 2020). "Among such loci identified by GWAS, chromosome 19q13 that carries genes, including TGFB1, B9D2 and TMEM91, has been reported to harbor multiple single-nucleotide polymorphisms (SNPs) that are linked to asthma, CF and/or COPD." (PMID 32500120, 2020).
neurological disorders (1 paper, 2022). "Of these, SH3BGRL3 has already been linked to SCZ and PSEN1, B9D2, and CXCR5 as well as DNAJB2 and were implicated in other neurological disorders." (PMID 36344995, 2022).
B9D2 also shares sentences with these, for which no sentence is quoted: autoimmune diseases of the thyroid (1 paper); Bardet-Biedl syndrome type 13 (1); Meckel syndrome, type 1 (1); retinal diseases (1); scoliosis (1).